INS (insulin)
Diseases named in the same sentence as INS in open-access papers (continued):
Sharing a sentence is not in itself a finding about the gene and the disease.
Obesity (continued). "Since hyperinsulinemia occurring in obesity significantly deteriorates insulin resistant states, LEAP-2 knockdown may pull down the excessive insulin secretion, thereby improve insulin sensitivity." (PMID 34512549, 2021). "As the focus of this study was to construct a systematic obesity-relevant metabolic network, we first checked the child’s clinical and biological parameters (leptin, OGTT insulin AUC, adiponectin, FFA, TNF-α, FPG, and total cholesterol) that are thought to be related to a change in BMI." (PMID 34946095, 2021). "We did not measure data of metabolic deregulation related with obesity, such as, serum levels of glucose, high-density lipoprotein cholesterol, insulin, triglycerides, low-density lipoprotein cholesterol, as well as total cholesterol." (PMID 34164233, 2021). "These relatively new categories of obesity came to light when noticing a subgroup of people with obesity, often early-onset, who have normal insulin sensitivity, and no signs of metabolic syndrome; “metabolically healthy” obesity." (PMID 33670215, 2021). "In contrast, in subjects with obesity, systemic levels of insulin, leptin, and resistin did not increase with gestational age, in line with reduced weight gain in this group." (PMID 34195568, 2021). "Fat cell lipolysis (i.e., fat cell triacylglycerol breakdown into fatty acids and glycerol in the absence of stimulatory factors) is elevated during obesity, and is correlated with insulin resistance." (PMID 34361788, 2021). "In addition to higher lipolysis and higher energy expenditure, deletion of GPR43 was also reported to improve the glucose homeostasis in obesity, as HFD-fed GPR43 KO mice exhibited lower body fat mass and increased insulin sensitivity." (PMID 34497585, 2021). "Among participants without obesity, HOMA-IR and insulin were both negatively associated with CERAD-IR and CERAD-DR." (PMID 34966358, 2021). "In our primary analysis we did not observe a significant difference in the direct comparisons of PPD in women with obesity who received insulin relative to women with obesity without treatment." (PMID 33743677, 2021). "The levels of FPG and HbA1c were similar between groups, whereas the values of HOMA-IR (p = 0.031) and insulin (p = 0.006) were different, so that the group of patients with obesity III exhibited the highest HOMA-IR value, and the group of patients with obesity II had the highest insulin value." (PMID 34578857, 2021). "Many of these obesity/T2DM-generated inflammatory signals converge to activate serine kinases promoting Ser phosphorylation of IRS1 (pSerIRS1), that directly interferes with insulin action in adipose tissue both in pathological and physiological conditions." (PMID 34071721, 2021). "It should be noted, however, that only very few studies included obese individuals, which is relevant because obesity has a much greater effect on the calculated insulin dose when this is based on body weight rather than on BSA." (PMID 33566134, 2021). "Under certain circumstances like obesity this could be an advantage, since PTP1B is known to regulate insulin signalling both in the central and peripheral systems, the CMV-RVG-siRP circuit could therefore restore insulin sensitivity to the maximum extent." (PMID 33782530, 2021). "JNK1 knockout mice exposed to a high-fat diet confers long-term metabolic protection from diet-induced obesity and display markedly improved insulin sensitivity with a normal life span." (PMID 34445300, 2021). "Among those: adiponectin, whose plasma concentration is reduced in obesity and T2DM, and inversely correlates with BMI and visceral fat, enhances insulin- mediated glucose uptake in skeletal muscle, increases insulin sensitivity in the liver, and decreases glucose production by gluconeogenesis." (PMID 33668627, 2021). "Several plausible mechanisms might explain the links between sleep, obesity and T2DM via changes in energy homeostasis, insulin resistance and beta-cell function." (PMID 34779405, 2021).
Obesity (continued). "A recent observational study showed that increased frequency of SMBG was associated with better glycemic control and more weight loss compared with less frequent SMBG among patients with T2DM and obesity irrespective of insulin use4." (PMID 33441946, 2021). "The primary objective was to investigate changes in substrate oxidation at rest and during exercise, and changes in insulin sensitivity for individuals living with or without obesity following 4 weeks of SIT." (PMID 34110721, 2021). "MetS diagnosis and HA at PCOS diagnosis were risk factors associated with NAFLD, while 2-h insulin level in 75 g GTT and obesity were not." (PMID 33782517, 2021). "have suggested that IR is closely related to incommensurate alterations to the composition of BA pool, and they have emphasized that increased BAs in IR, rather than obesity possibly contribute to the defects in insulin signaling." (PMID 34675887, 2021). "Because of this, PTHrP might be used in obesity treatment for its ability to reprogram adipogenesis and adipose tissue expansion, favoring lipolysis, WAT browning and the improvement of the insulin sensitivity." (PMID 34827568, 2021). "PTHrP might be used in obesity treatment and its complications for its ability to reprogram adipogenesis and adipose tissue expansion, WAT browning and for the improvement of the insulin sensitivity." (PMID 34827568, 2021). "Apart from using alone, mulberry leaf extracts combined with mulberry fruit extract also exhibited anti-obesity effects in HFD-induced obese mice, as evidenced by decreased body weight gain, improved fasting plasma glucose and insulin, and alleviated inflammation and oxidative stress." (PMID 34631766, 2021). "However, the rescue of human PL gene expression seen in women with obesity that develop GDM and are treated with insulin, is consistent with rescue of both lactogenic signaling via the prolactin receptor and related negative effects in the maternal brain." (PMID 33743677, 2021). "However, an increased amount of circulating insulin and free IGF-I has been related to physical inactivity and obesity." (PMID 34298805, 2021). "Though this would suggest that DCs play a deleterious role in obesity, Macdougall and colleagues revealed that VAT conventional DCs subsets actively suppress AT inflammation and promote insulin sensitivity in homeostatic lean conditions via PPARγ and the Wnt/β-catenin pathway." (PMID 34613819, 2021). "In vitro studies of insulin-resistant human hepatocytes showed THCV restoration of insulin signaling mediated by CB1, while also improving glucose tolerance and increased sensitivity to insulin in mice obesity models." (PMID 33652704, 2021). "Importantly, BKO mice already showed increased β-cell proliferation and glucose-stimulated insulin secretion with respect to WT littermates after two weeks of HFD feeding, before the onset of obesity." (PMID 34015524, 2021). "It is caused by a combination of genetic factors related to impaired insulin secretion and IR, by environmental factors, such as obesity, lack of exercise, and stress, as well as by aging, indicating that T2DM is a multifactorial disease." (PMID 33918509, 2021). "Additionally, other parameters related to obesity or metabolic syndrome, such as Leptin, IGF, Insulin, or Adiponectin were measured during postnatal ages." (PMID 34281107, 2021). "Although we observed an improvement in fasting glucose and whole body insulin sensitivity and a reduction in angiogenesis with moringa alone, moringa seed extract did not reduce tumor volume in mice with diet-induced obesity compared to other treatment groups." (PMID 34578801, 2021). "Obesity induced by fat dietary results in beta cell hyperplasia but not in enhanced insulin release in mice." (PMID 34944525, 2021).
Obesity (continued). "Previous studies showed that enhanced glucose intake in transgenic mice expressing human GLUT4 under its own promoter improved insulin sensitivity, but reduced lipid oxidation in the skeletal muscle and did not alleviate obesity under HFD." (PMID 34227742, 2021). "The resulting lowering of blood glucose, insulin and body weight reverses IR, T2DM, AND obesity." (PMID 34447776, 2021). "Previous studies have observed that obesity induces proliferation of β cell mass but does not alter the capacity of insulin secretion, possibly due to these dual effects of ATM EVs on β cell insulin secretion and proliferation." (PMID 34572101, 2021). "This is consistent with the observation that BCAA excursions during an oral glucose tolerance test are not an independent predictor of glucose tolerance, insulin sensitivity and β-cell function among mostly non-Asian adolescents with obesity." (PMID 33996878, 2021). "Nevertheless, some patients with obesity can demonstrate a “metabolically healthy” phenotype during a long time without any alterations in carbohydrate metabolism and insulin sensitivity." (PMID 34956089, 2021). "Such an impact could be assigned to elevated insulin levels, androgens, and free IGF-I due to obesity." (PMID 34758846, 2021). "An LCD should be discussed with every patient with T2DM, especially those on insulin, and a referral to an obesity medicine specialist should be made if the provider is not comfortable managing the dietary intervention." (PMID 34458301, 2021). "Feeding the mice HFKV over 12 weeks or introducing HFKV only in the last 6 weeks after inducing obesity with HFD did not lower fasting insulin compared to that of mice fed HFD only." (PMID 34432833, 2021). "From all these findings, we are able to conclude that obesity, per se, is not an independent prognostic factor in BC, whereas plasma insulin levels and insulin resistance seem to be related to BC prognosis." (PMID 33477996, 2021). "Reddy and colleagues have reported increased ER stress markers, such as ATF6, IRE1, and CHOP, in the cortex of WNIN/ob rats, a mutant obese strain that develops spontaneous obesity with insulin and leptin resistance independent of HFD exposure." (PMID 33092099, 2020). "Obesity and visceral obesity are also central components of metabolic syndrome with an important role in CVD through different mechanisms such as insulin resistance and the induction of a proinflammatory state." (PMID 32466598, 2020). "We found that obesity starting in the young age has deep consequences on the maturation of the pancreas innervation (density and PINS phenotype) and the nervous control of insulin secretion." (PMID 31922022, 2020). "More importantly, we aimed to have a look at the effect of exosomes from obese and non-obese women to disclose the role of obesity in regulating insulin signaling and the secretion of hepatokines." (PMID 32322309, 2020). "In obesity, non-esterified fatty acids and insulin inhibit IGFBP production, which increases free IGF-1 in circulation." (PMID 32586279, 2020). "NLRP3 inflammasome ablated mice do not show obesity-induced inflammasome activation in both fat depots and liver and present better insulin signaling." (PMID 32012784, 2020). "Altogether, our study has demonstrated that chrysophanol can inhibit lipid accumulation and prevent obesity by activating the brown adipocyte SIRT6/AMPK signaling pathway, increasing adipose decomposition, FAO, improving insulin sensitivity and thermogenesis in HFD-induced obese mice." (PMID 33274005, 2020). "In HFD‐induced obesity, coupled with insulin desensitization, we found no favorable effect of succinic acid on glucose regulation, though adiposity was attenuated." (PMID 33185326, 2020). "The potential adverse effects of high sugar-containing pomegranate juice was highlighted in a clinical trial that revealed that pomegranate juice administration over one month did not modify insulin secretion and sensitivity in patients with obesity." (PMID 32751794, 2020).
Obesity (continued). "Maternal pre-pregnancy BMI was increased (mean ± SD; 30.7 ± 5.6 kg/m2), 128 women had pre-pregnancy obesity, and 96 were diagnosed with GDM in the indexed pregnancy (including 36 on metformin or insulin): 61 in first trimester, 32 in second trimester, and three in third trimester." (PMID 32725413, 2020). "To further elucidate the potential role of adipose tissue function in defining metabolic health despite obesity, we studied pairs of individuals with MHO, which have been matched for age, gender, and BMI, but were either insulin sensitive or resistant in euglycemic-hyperinsulinemic clamps." (PMID 32128581, 2020). "C-peptide, insulin, glucose, HbA1c, uric acid, fibrinogen, free triiodothyronine, albumin, gamma glutamyl transferase (GGT), and alkaline phosphatase are the top ten ranked biomarkers for obesity (based on p-value)." (PMID 33138081, 2020). "Because obesity and T2DM share some biological features such as elevated insulin levels, hypertension, and chronic inflammation and since higher BMI has been associated with increased incidence of T2DM, we explored a possible interaction between the two risk factors." (PMID 33198768, 2020). "Similar to insulin (INS), increased postprandial TRL are also considered as a key natural inducer of adipogenic differentiation, which is one of the important mechanisms of obesity." (PMID 33316776, 2020). "Thus, Sechium edule consumption can be considered as a therapeutic agent with beneficial effects on insulin sensitivity, T2DM, and obesity." (PMID 32708368, 2020). "Children with PWS are more insulin sensitive and less insulin resistant than children with non-syndromal obesity." (PMID 33046090, 2020). "The IVAT area evaluated by MRI was a major predictor of peripheral and hepatic insulin action in 57 participants with obesity, whereas the RVAT area was not." (PMID 33292449, 2020). "Therefore, HSL and insulin play an important role in the regulation of various metabolic disorders including lipotoxicity, T2DM, IRes, inflammations, steatosis, NAFLD, and obesity." (PMID 33322719, 2020). "This is not unlikely, because in obesity-induced steatosis, it is insulin resistance in adipocytes that contributes to steatosis." (PMID 32443737, 2020). "Under insulin‐stimulated conditions, paternal obesity augmented p‐AKTSer473 while p‐AKTThr308 did not change." (PMID 32539156, 2020). "In obesity, white adipose tissue becomes resistant to the antilipolytic effect of insulin, and the concentration of non-esterified fatty acids (NEFA) increases." (PMID 32117058, 2020). "We have shown that in a predominantly white cohort of adults with severe obesity who underwent laparoscopic sleeve gastrectomy, there was a substantial reduction in the LAR after 12 months, which may indicate an increase in insulin sensitivity." (PMID 33004989, 2020). "Adipose tissue depot influenced adipocyte glucose uptake independent of obesity, with basal and insulin-stimulated glucose uptake decreased in VAT relative to SAT adipocytes in both ND and HFD states." (PMID 32272860, 2020). "Not all obesity patients are insulin resistant, thus he interconnections involved need to be further explored." (PMID 33324553, 2020). "Whole-body PTP1B-knockout mice are resistant to high fat-induced obesity with enhanced insulin sensitivity and do not develop T2DM." (PMID 32438641, 2020). "The same results were observed in a mouse model of diet-induced obesity, using isorhamnetin glycosides extracted from OFI, or using different bioactive compounds extracted from seaweed or ginseng leaf or Korean red ginseng on insulin sensitivity." (PMID 32024512, 2020). "Finally, mice with tissue specific double knockout of insulin and IGF-1 showed a significant decrease in both white and brown fat mass, and were resistant to high fat diet-induced obesity and glucose intolerance." (PMID 32560163, 2020).
Obesity (continued). "In contrast, no reductions in fasting insulin were shown, which is in line with previous observations made in males with obesity after a standardized fast." (PMID 32729615, 2020). "Finally, our results indicate that exquisite control of the concentration of insulin (control nutrients intake) or function of insulin signalling (certain natural compounds) may be a new potential strategy to regulate preadipocyte differentiation, adipocyte dedifferentiation and obesity development." (PMID 31989870, 2020). "Collectively, these data demonstrate that pharmacologic mitochondrial uncoupling with BAM15 has powerful anti-obesity and insulin sensitizing effects without compromising lean mass or affecting food intake." (PMID 32409697, 2020). "We also observed that ADH1B protein and mRNA expression levels decreased with obesity, but BS restored and even exceeded the values of the control group, demonstrating a negative correlation with BMI, insulin sensitivity and adipocytes size." (PMID 31941045, 2020). "After high-fat feeding, IGFBP-1-KO mice had comparable body mass, glucose homeostasis, and insulin sensitivity, indicating that IGFBP-1 is not causally implicated in protection from obesity and obesity-impaired glucose tolerance." (PMID 32190801, 2020). "Supplementing HFD with 6% CSF stabilized gut microbiota composition, and improved insulin sensitivity of obese mice, although no impact on obesity phenotype was observed." (PMID 32013093, 2020). "In an HFD model of obesity in Swiss mice, the administration of CGS21680, an A2aAR agonist, improved glucose homeostasis, as determined by insulin tolerance test, and reduced inflammatory markers such as tumor necrosis factor alpha (TNFα) systemically and in the visceral adipose tissue." (PMID 33050467, 2020). "We propose that the changes in the community of fecal microbes caused by an obesogenic diet is a stand-alone factor that can impair insulin clearance without altering C-peptide clearance or the extent of obesity." (PMID 32860984, 2020). "The anti-oxidative, anti-obesity, and anti-diabetic potential of BCB was checked in the various diabetic model mice, where BCB increased serum insulin secretion with reduced pro-inflammatory cytokine expression (MAPKs, NF-κB, COX-2, and iNOS) in a dose-dependent manner." (PMID 32825710, 2020). "Therefore, research is ongoing to identify new targets to develop safer and more effective anti-obesity and anti-NASH drugs by improving energy metabolism, insulin sensitivity and inflammation." (PMID 32204420, 2020). "It has also been reported that individuals with T2DM tend to have elevated FFA levels over non-diabetic controls, an effect found to correlate more strongly with insulin sensitivity rather than obesity." (PMID 32158768, 2020). "However, VAT mRNA expression of TUG1 had a positive correlation with obesity indices and HOMA-IR and insulin levels in the whole population." (PMID 32368256, 2020). "Due to the important role skeletal muscle plays in insulin‐stimulated glucose disposal, obesity and a HFD can negatively impact the mitochondrial content of the muscle and thus hinder its function." (PMID 33185326, 2020). "The link with insulin sensitivity rather than with obesity further supports the need to look into obese phenotypes, since the visceral obese inflamed phenotype is also related to the presence of insulin resistance." (PMID 31947724, 2020). "We analysed serum haemoglobin A1c (HbA1c) levels, the incidence of severe hypoglycaemic events, the types and doses of insulin, height standard deviation scores (SDS), body mass index (BMI) percentiles compared with healthy Japanese children and obesity prevalence over time." (PMID 33227006, 2020). "We found significantly higher values in BMI, waist-hip ratio (WHR), and waist circumference as well as in CRP, white blood cell, glucose, and insulin levels and HOMA-IR, in both groups of patients with obesity compared with lean patients, whereas HDL levels were decreased." (PMID 32244612, 2020).